LAG3 (lymphocyte activating 3)
Diseases named in the same sentence as LAG3 in open-access papers (continued):
Sharing a sentence is not in itself a finding about the gene and the disease.
tumor (continued). "Further studies would be needed to ascertain the expression characteristics of LAG-3 and its ligands on non-immune cell types, such as stromal, vascular, and tumor cells." (PMID 37795090, 2023). "In contrast to TIM-3, no studies have reported the mechanism by which LAG-3 expressed on tumor cells promotes the proliferation of these cells." (PMID 37670328, 2023). "In the untreated tumor, half of all T cells belonged to the exhausted CD8+ T cell cluster, characterized by expression of residence and checkpoint molecules such as PD-1, TIGIT, CTLA-4, LAG-3, CD69, and CD103." (PMID 37209684, 2023). "Further analysis of tumor-infiltrating CD8+ T cells revealed a less exhausted phenotype, with a significant reduction in the fraction of Tim3+, LAG3+, Blimp1+, and EOMES+ as well as annexin V+ CD8+ T cells, but with a modest increase in T-bet+ cells (P = 0.1878) and CD44+CD8+ T cells." (PMID 38038129, 2023). "A second PD1 expressing, LAG3-low host T cell cluster (cluster 5), which likely comprises non-exhausted T cells that are actively engaging tumor cells, was notably present in the SIVET conditions with a higher enrichment relative to the TcellOnly_Depot." (PMID 37322053, 2023). "This indicated that repetitive antigenic stimulations may up-regulate the expression of negative regulatory markers (e.g., PD-1, LAG-3, TIM-3) among the tumor-infiltrating lymphocytes, leading to an elevated immune suppressive microenvironment." (PMID 37514985, 2023). "Furthermore, depletion of B and T cells mitigated the antitumor effects of FGL1 and LAG-3 inhibition, suggesting that FGL1 contributes to tumor growth by inhibiting antitumor immunity." (PMID 37115694, 2023). "Although adaptive NK cells can effectively kill tumor cells, they have a limited proliferative capacity and, hence unsurprisingly, did not expand following anti–LAG-3+anti–PD-1 therapy." (PMID 36719749, 2023). "Another limitation is that tumour-infiltrating lymphocytes would be more ideal than PBMCs for studying the immune landscapes of LAG3+ cells, but we did not have access to tumour-infiltrating lymphocytes from the same patients." (PMID 37342338, 2023). "When we assessed LAG-3 expression in each subset as a proportion of the total tumor infiltrating T cells, the CD8 TEM cells were found to constitute the bulk of LAG-3+ T cells within the tumor microenvironment, with a median frequency of 3.6% (range = 0.2% – 32.9%)." (PMID 37795090, 2023). "ICB therapy is an emerging immunotherapy aiming at blocking immunosuppressive tumor signals and restoring anti-tumor immune responses by targeting checkpoint receptors or ligands such as PD-1/PD-L1, CTLA-4, TIGIT, LAG-3, TIM3, among which PD-1/PD-L1 is the most common research object." (PMID 38283361, 2023). "Relatlimab (OPDUALAGTM, mAbID 781), recently approved by FDA in 2022, binds to LAG3 overexpressed by T cells in the TME and blocks its binding to its ligands, activating exhausted T cells and enhancing the CTL-mediated immune response against tumor cells." (PMID 37215135, 2023). "In addition, studies have identified the synergistic effect of LAG3 and PD1 in mediating T-cell exhaustion, thereby weakening anti-tumor activity." (PMID 36816967, 2023). "Furthermore, a strong significant correlation was observed in CD127 MFI (r = 0.82; p < 0.0001) and in LAG3 MFI (r = 0.76; p < 0.0001) of CD8+ lymphocytes between tumor and peripheral blood." (PMID 36900156, 2023). "Nevertheless, other studies have found that IFN‐γ in TME may also promote the expression levels of inhibitory receptors, such as PD‐1, PD‐L1, LAG‐3, and TIM‐3, which have been proven to help tumor escape." (PMID 37829505, 2023). "When we analyzed the PD-1+ LAG-3+ CD8 TCM and TEM subsets as a proportion of the total tumor infiltrating CD8 T cells, we found that the double positive TEM cells constituted a sizeable minority of the population, with a median frequency of 14.0% (range = 4.1% – 42.1%)." (PMID 37795090, 2023).
tumor (continued). "The expression of inhibitory molecules, such as CTLA-4, PD-1, LAG-3, Tim-3 and TIGIT, is crucial for the suppressive activity, making Tregs suppression via checkpoint inhibition a possible approach to promote an efficient anti-tumor immune response." (PMID 37371818, 2023). "The antibodies anti-CTLA-4, anti-PD-L1 and anti-LAG-3 with anti-PD-L1 also strongly inhibited tumor growth and enhanced survival in the absence of PDT, albeit to a lesser extent." (PMID 36997666, 2023). "Besides PD-1/PD-L1, CTLA-4, antibodies against three promising inhibitory receptors, LAG3, TIM-3, and TIGIT expressed on tumor-infiltrating lymphocytes (TILs) are under intense clinical development." (PMID 36810034, 2023). "Further membrane proteins that shared robust expression in EBV+ tumor samples and low/absent levels in most healthy tissues included PD-L1, PD-L2, LAG3, TIM3 as well as B-cell marker CD19." (PMID 37495858, 2023). "Recent studies have highlighted novel associations with immune checkpoints proteins that could be useful such as LAG3, TIM3, or TIGIT due to their expression levels within tumours." (PMID 37608028, 2023). "We used TISIDB database to predict and analyze the correlation between CHSY1 expression and immune factors including PD-L1, PD1, LAG3, IDO1 and CTLA4, so that we could observe the interaction between CHSY1 and the CRC tumor microenvironment." (PMID 37749638, 2023). "Of note, they observed high levels of TIL ‘exhaustion markers’ such as PD-1 and LAG-3 post infusion, as well as increased expression of MHC-II and PD-L1 in the tumour tissue, which may be impeding the efficacy of the treatment." (PMID 37835509, 2023). "The membrane-bound MHC II (a possible ligand of LAG-3) on the tumor cells did not correlate with sLAG-3." (PMID 37174080, 2023). "Lymphocyte activation gene-3 (LAG-3; CD223), a member of the immunoglobulin superfamily, is expressed on exhausted or dysfunctional T cells, and it is a therapeutic target for reinvigoration of anti-tumor immunity." (PMID 37857711, 2023). "Blockade of PD-1 and LAG-3 in animal tumor models generated enhanced anti-tumor immunity via distinct, non-redundant signaling pathways that fostered the accumulation of functionally competent CD8+ T cells in mice." (PMID 37857711, 2023). "In our research, well-known immune checkpoint molecules such as PD-1, PD-L1, CTLA-4, and LAG-3 were not highly expressed in the tumor tissues." (PMID 37511338, 2023). "Moreover, using the same cutoff of 1%, we found that ICB-treated HCC patients with high LAG-3+ cell proportions in the tumor microenvironment had significantly longer PFS and OS, compared to patients with low LAG-3+ cell proportions." (PMID 37342338, 2023). "A great range of immune checkpoint molecules, such as PD-1, PD-L1, CD73, Lag-3, B7-H3, TIM-3, CTLA-4, TIGIT, and VISTA in the tumor microenvironment (TME) are involved in important mechanisms that prevent effector T cells’ anti-tumor activities." (PMID 37008041, 2023). "We speculated that the ligands of NPC tumor cells may bind to various inhibitory receptors of NK cells, such as TIGIT, LAG3 and TIM-3, and reduce the cytotoxicity of NK cells." (PMID 37098551, 2023). "Marker signal intensity profiles of the PD-1+ LAG-3+ subset from both CD8 TCM and TEM were distinct from that of the profiles of cells that expressed either PD-1 or LAG-3, or were negative for both, which was observed across tumor types." (PMID 37795090, 2023). "A breakdown of all the ligands targeting the LAG3 receptor on CD8+ T cells, regardless of cancer cell EMT status or tumor immune phenotype, showed that most ligands for LAG3 are HLA II molecules, with LGALS3 being the only non-MHC related ligand." (PMID 38086828, 2023). "The presence of CD8+ T cells expressing inhibitory markers such as LAG3, TIGIT, KLRC1, and PD-1, and FOXP3+ regulatory CD4+ T cells may prevent effective T cell–mediated tumor control in PDAC." (PMID 37751306, 2023).
tumor (continued). "As crucial immune checkpoint molecules, T-cell inhibitory receptors, including CTLA-4, PD-1, TIM-3, LAG-3, and TIGIT, are essential in limiting immunopathology and terminating effective immune response, while they can also inhibit effective anti-tumor immunity." (PMID 37056782, 2023). "Moreover, risk scores were negatively related to the expression of CD274, CTLA4, ICOS, LAG3, PDCD1, and PDCD1LG2 and negatively correlated with CD8+, CD4+, and Treg tumor-infiltrating immune cells." (PMID 37674251, 2023). "For in vivo validation, AGK2 or aspirin treatment exhibited comparable efficacy with anti–LAG-3 mAb in suppressing tumor growth, and we detected no statistical significance between these 3 therapeutic strategies." (PMID 37115693, 2023). "Several preclinical studies have demonstrated that targeting LAG-3, TIM-3, or TIGIT restores T cell function and inhibits tumor progression, and most studies indicated that coinhibition of different ICPs may effectively enhance antitumor activity." (PMID 37670328, 2023). "Malignant cells themselves, or lymphocytes that infiltrate tumors, can abnormally express a variety of immune checkpoint molecules, including PD-1/PD-L1, LAG-3, TIM3, and TIGIT, which inhibit the activation of antigen-specific T cells and facilitate tumor cell immune escape." (PMID 38106403, 2023). "Our study showed that NK cell inhibitory receptors such as TIGIT, LAG3 and TIM-3 were all upregulated and that exhaustion of NK cell may induce immune escape and tumor progression in NK-NPC." (PMID 37098551, 2023). "Clinical trials have shown that LAG-3 blockade as a cancer treatment activates APC to promote DCs proliferation and enhances regulatory T cell immunosuppression and antigen cross-presentation to CD8+ T cells, promoting an anti-tumor state." (PMID 36680187, 2023). "When LAG‐3 is overexpressed in T‐cells around tumor cells (tumor infiltrating lymphocytes; TIL), it can contribute to immune evasion of tumors by inhibiting the recognition of tumor antigens by the host immune system." (PMID 37326144, 2023). "Nevertheless, the expression of exhaustion-associated proteins in tumor-infiltrating CD8+ T cells — including immunosuppressive receptors PD-1, TIM-3, TIGIT, and LAG3 — were not affected by Rig-I deficiency." (PMID 36927693, 2023). "In addition to immune checkpoints (PD-L1/L2, LAG3, TIM-3) strongly expressed IL1R2 and CD70 can inhibit immune responses and create a tolerogenic tumor microenvironment (TME)." (PMID 37495858, 2023). "This may be explained in part by their high affinity for PD-L1 on tumor cells but low to medium affinity for TIGIT and LAG-3 on T cells." (PMID 37332070, 2023). "In addition, overexpression of DSE promoted the overexpression of tumor killer molecules such as GZMB, TNF and IFNG in CD8 + T cells, and inhibited the expression of inhibitory molecules such as PD-1, TIM-3 and LAG-3." (PMID 37833287, 2023). "Galectin-3, a ligand expressed by numerous cells within the tumor microenvironment rather than the tumor itself, has the potential to interact with LAG3 on tumor-specific CD8+ T cells, thereby modulating anti-tumor immune responses." (PMID 37569880, 2023). "Analysis of tumor specimens obtained before and after CAR-T cell therapy (but before tebotelimab treatment) demonstrated a dynamic immune activation in the TME after CAR-T cell therapy, as evidenced by increased TILs and upregulation of LAG-3 and PD-1." (PMID 37857711, 2023). "Immunohistochemical scoring of pre-treatment levels of LAG-3 and CD8 in the tumor microenvironment may help predict ICB benefits in HCC patients." (PMID 37342338, 2023). "Despite the increased PD1 levels, an improved PD1+CD28+ T-cell polyfunctionality was observed with the transition from periphery to tumor site, associated with lack of TIGIT, TIM-3 and LAG-3, but not with Ag-experienced-marker CD11a." (PMID 37898752, 2023).
tumor (continued). "We have obtained a predictive model for TNM which combines peripheral blood parameters (% CD27+ CD4+ lymphocytes, % IDO+ monocytes, LAG3 MFI in CD4+ lymphocytes) with histological grade and tumor size and discriminates pTa and pT1 tumors with a sensitivity of 75% and specificity of 96.65%." (PMID 36900156, 2023). "Given the unique role of immune checkpoint molecules in tumor immune microenvironment (TIME), we explored the expression of PD-1, PD-L1, LAG3, GAL9 and CTLA4 and found that the expression of these molecules was significantly elevated in pyrocluster A than that in pyrocluster B." (PMID 37221570, 2023). "Meanwhile, the emergence of RUNX1 mutation, upregulations of genes expression (RPS27A, RPS6, UBA52, RACK1) on tumor cells, and increased frequencies of T and NK cells with TIGIT, CTLA4, and LAG3 expression were observed after midostaurin treatment, predicting the disease progression of this patient." (PMID 37638009, 2023). "Notably, the targets of most of the current immuno-oncology agents, such as PD-L1, CTLA-4, LAG-3 and TIM-3, express on the cell surface and can directly mediate tumor-immune interactions." (PMID 34980132, 2022). "Altogether, our study represents a first demonstration that the combination of T cell-mediated immunotherapy with genetic ablation of PD-1, LAG-3, and TIM-3 could delay tumor progression and significantly improve survival." (PMID 35328630, 2022). "We believe that even in these patients with no response to PD-1/PD-L1 inhibitors, FGL1/LAG-3 is involved in the suppression of anti-tumor immunity and results in therapeutic effect." (PMID 35273912, 2022). "In Rag1−/− mice co-transplanted with RAMP1-expressing and -non-expressing CD8+ T cells, we found that within the same tumour, the relative proportion of intratumoral PD-1+LAG3+TIM3+ CD8+ T cells was lower in Ramp1−/− CD8+ T cells." (PMID 36323780, 2022). "Moreover, we observed higher levels of inhibitory receptors such as PD1, TIM3, LAG-3, and a decreased proliferating capacity of 4T1-specific CD8+ T cells at the tumor site in control mice." (PMID 35915084, 2022). "Both CD8+ and CD4+ Tcells also showed increased expression of the immune checkpoint molecules PD-1,LAG-3 and TIM-3 in KPAR tumours.Furthermore, KPAR tumours also contained a significant proportion of PD-1/LAG-3double-positive CD8+ T cells which were completely absent in KPB6tumours." (PMID 35930804, 2022). "In the tumor microenvironment, the ratio of CD8+ T cells to CD4 + FOXP3+ regulatory T cells was significantly elevated and exhausted CD8+ T cells (PD-1+, CTLA-4+, TIM-3+, or LAG-3+ cells) were significantly reduced in the triple combination group." (PMID 35681672, 2022). "In addition, WT ARI-0001 and TCRKO ARI-0001 CAR-T cells shared a comparable expression of LAG3 and TIM3 exhaustion markers after tumor cells killing as well as similar production of interferon (IFN)-γ and tumor necrosis factor (TNF)-α." (PMID 36275777, 2022). "In addition, an anti-PD-1/LAG-3 bispecific antibody trial is also recruiting (NCT04140500) based on data that antibody targeting of PD-1 and LAG-3 synergistically inhibited tumour growth in vivo." (PMID 35265944, 2022). "CB-specific T cells primed in wild-type mice and transferred into tumor-bearing Batf3–/– mice did not acquire Foxp3 or the Klrg1+Lag3+ subset." (PMID 35393950, 2022). "Interestingly, we also observed a parabolic expression in genes involved in immune exhaustion (e.g. TCF7, LAG3, CTLA4 and PDCD1), which is consistent with the peak of immune landscape remodelling at S2 tumours as shown by our data above." (PMID 35301339, 2022). "As with prior adjuvant trials, RELATIVITY-098 (NCT05002569) a phase 3 trial comparing combination relatlimab (anti-LAG-3) and nivolumab to nivolumab alone in the adjuvant setting utilizes stage IIIA with at least 1 mm nodal tumor deposit as the threshold for inclusion." (PMID 36411863, 2022).
tumor (continued). "At the same time, the overall survival rate significantly increased after simultaneous genetic editing of PD-1, LAG-3, and TIM-3, which is in line with previous literature showing reduced tumor growth and increased survival after ATT with double knockout (LAG-3 and PD-1) T cells." (PMID 35328630, 2022). "In concert, the increased Renilla Luciferase signal at the tumor site in the animals treated with 3KO OT-1 CD8+ T cells supports the conclusion that the genetic ablation of PD-1, LAG-3, and TIM-3 improves the ability of the CD8+ T cells to enrich in the tumor and to persist at the tumor site." (PMID 35328630, 2022). "LAG-3 antibody C9B7W could block the binding of LAG-3 to the LSECtin, inhibit the proliferation of effector T cells and the growth of transplanted tumor." (PMID 36358719, 2022). "Combination therapy of LAG3 blockade and MWA was a unique therapeutic regimen for some solid tumors, and such combination therapy might reprogram the TME to an anti-tumor manner." (PMID 36180876, 2022). "Immune checkpoints such as Programmed Cell Death Protein 1 (PD-1), T cell immunoglobulin domain and mucin domain-3 (TIM-3), and Lymphocyte activation gene-3 (LAG-3), which are often activated in the tumor tissue and regulate T-cell function, are important immunotherapy targets." (PMID 35936682, 2022). "Combination of immunotherapy, such as antibody against PD-1/PD-L1 with antibody against LAG3, TIM3, or CTLA4, could further increase tumor-infiltrating lymphocyte functions." (PMID 35892867, 2022). "Antibodies against LAG-3, TIM-3, TIGIT, CD47, and B7-H3 are the most advanced IC blockade drugs and may be approved for the treatment of specific tumor types in the near future, depending on the results of the trials." (PMID 35164813, 2022). "Similar tendencies were observed in a study conducted on 53 patients with NSCLC, where intratumoral Treg cells presented higher levels of immunosuppressive molecules, such as LAG-3, CTLA-4 and PD-1 than Tregs from tumor-adjacent tissues or peripheral blood Treg cells." (PMID 36077354, 2022). "Tumor cells can escape the killing of tumor cells by T cells through downregulating MHC and upregulating the expression of inhibitory receptors such as PD-L1, CTLA-4, LAG-3, TIM-3 and TIGIT, and blocking the binding of these inhibitory receptors to ligands can restore T-cell anti-tumor activity." (PMID 36225938, 2022). "Besides, the expression of cell exhaustion-related genes, including PDCD1, CTLA4, LAG3, and TIGIT, was upregulated in several tumors, indicating that UBE2S was intensely involved in tumor evasion via different mechanisms." (PMID 35578600, 2022). "Supervised flow cytometry analyses showed that (i) most CD3+ TILs expressed PD-1 and TIGIT and, to a lesser extent, Tim-3, Lag3 and NKG2A, and (ii) EpCAM+ tumor cells and CD11b+ myeloid cells differed in their IC ligand expression profile, with a strikingly high expression of CD155 by tumor cells." (PMID 36077799, 2022). "In addition, nociceptor-ablated mice showed an increase in the total number and relative frequency of cytotoxic (IFNγ+, TNF+or IL-2+) tumour-infiltrating CD8+ T cells, but a reduced proportion of PD-1+LAG3+TIM3+ CD8+ T cells." (PMID 36323780, 2022). "While the exact mechanisms of LAG-3 remain controversial, this immune checkpoint has gained prominence with the development of relatlimab (anti-LAG-3 antibody) which has recently been shown to improve anti-tumor activity in combination with nivolumab." (PMID 36466880, 2022). "This bispecific molecule binds and blocks with high affinity PD1 and LAG-3 on PD-1+LAG-3+ T cells, induces ex vivo T cell proliferation of dysfunctional T cells from NSCLC patients, with superior activity than anti-PD-1 alone and suppress tumor growth in vivo." (PMID 35954196, 2022).